GREB1 (growth regulating estrogen receptor binding 1)
Diseases named in the same sentence as GREB1 in open-access papers (continued):
Sharing a sentence is not in itself a finding about the gene and the disease.
melanoma (continued). "Conversely, overexpression of wild-type (WT) MITF in non-melanoma 293T cells increased GREB1 Is4, PMEL, and MLANA mRNAs." (PMID 37658191, 2023). "GREB1 was highest in hormone-responsive cancers (ovarian, uterine, breast, prostate) and unexpectedly, melanoma." (PMID 29973689, 2018). "Because MITF is essential for melanoma development and GREB1 expression, GREB1 may mediate MITF-dependent melanomagenesis." (PMID 37658191, 2023). "Furthermore, among the top 25 genes highly correlated with GREB1 gene expression in melanoma, 16 genes were known targets of MITF, such as MLANA and PMEL." (PMID 37658191, 2023). "Functionally, GREB1 Is4 expression stimulated melanoma cell proliferation." (PMID 37658191, 2023). "Both in vitro and in vivo, the GREB1 Is4 expression stimulated melanoma cell proliferation." (PMID 37658191, 2023). "Taken together, these results indicate that GREB1 Is4 mRNA is uniquely transcribed in melanoma." (PMID 37658191, 2023). "Finally, to examine the role of GREB1 Is4-dependent pyrimidine metabolism in melanoma cell proliferation, the effects of A771726 (DHODH inhibitor) on cell viability in GREB1 Is4 KD melanoma was examined." (PMID 37658191, 2023). "Similarly, analysis of the melanoma TCGA dataset revealed that GREB1 gene expression was positively correlated with the expression of proliferative marker genes (CDK2, MYC, CCND1, and LIG1) and negatively correlated with CDKN1B." (PMID 37658191, 2023). "Indeed, MITF and GREB1 Is4 were co-expressed in melanocytic melanoma cells lines and in 40% of benign nevi, and 20% of melanoma tumors." (PMID 37658191, 2023). "Furthermore, the FANTOM5 SSTAR (Semantic catalog of Samples, Transcription initiation And Regulators) data revealed that transcription initiation of GREB1 Is4, denoted as p2@GREB1, primarily occurs in melanoma and melanocytes among various human primary cell types, cancer cell lines, and tissues." (PMID 37658191, 2023). "Consequently, targeting GREB1 offers a new and unique approach to inhibit melanoma growth." (PMID 37658191, 2023). "We found that GREB1 Is4 is localized to the cytosol of cells and binds to CAD in melanoma cells, resulting in positive cooperation for pyrimidine biogenesis." (PMID 37658191, 2023). "Expression of GREB1 and MITF in benign nevi (N = 20) and primary melanoma tumors (N = 89) was analyzed by immunohistochemistry (IHC)." (PMID 37658191, 2023). "Tyr-CreER; BRAFV600E; PTENflox melanoma mice were crossed with the Is4+/− mice, generating control (Tyr-CreER; BRAFV600E; PTENflox; Is4−/−) and GREB1 Is4 (Tyr-CreER; BRAFV600E; PTENflox; Is4+/−) mice." (PMID 37658191, 2023). "Thus, GREB1 Is4 may have unknown functions in the cytosol of melanoma cells." (PMID 37658191, 2023). "When GREB1 Is4 was expressed in the neonatal stage of BRAFV600E; PTENflox mice, it promoted the formation of BRAFV600E; PTENflox melanoma." (PMID 37658191, 2023). "The TCGA dataset showed that in addition to hormone-dependent tumors, such as prostate (PRAD), breast (BRCA), endometrial (UCEC), or ovarian (OV) cancers, GREB1 mRNA is highly expressed in skin (SKCM, melanoma) cancer." (PMID 37658191, 2023). "High GREB1 and MITF expression levels were observed in 7/63 cases (11.1%) and 31/63 cases (49.2%), respectively, of primary melanoma with a depth over 1.5 mm." (PMID 37658191, 2023). "In addition, TCGA dataset showed that GREB1 Is4 mRNA transcription from exon 19 was elevated only in Skin-SKCM and Uveal-UVM melanomas among 11 cancers." (PMID 37658191, 2023). "GREB1 Is4 was highly expressed with MITF in both benign nevi and melanoma samples." (PMID 37658191, 2023). "For melanoma cases with a depth of less than 1.5 mm, none had high GREB1 expression (0/26), while only 11.5% (3/26) of these cases had high MITF expression." (PMID 37658191, 2023). "Consistently, mouse GREB1 isoforms equivalent to human GREB1 Is4 were not reported in the Ensembl data, indicating that GREB1 Is4 expression is specific to human melanoma." (PMID 37658191, 2023).
melanoma (continued). "Because the targeting of GREB1 Is4 could inhibit melanocytic melanoma growth in a different way from BRAF or immune checkpoint inhibitors, it paves the way for new clinical trials to eradicate malignant melanoma." (PMID 37658191, 2023). "In addition, GREB1 Is4 targeting by antisense oligonucleotide (ASO) decreased melanoma xenograft tumor formation and GREB1 Is4 expression in a BRAFV600E; PTENflox melanoma mouse model promoted melanoma formation, demonstrating the crucial role of GREB1 Is4 for melanoma proliferation in vivo." (PMID 37658191, 2023). "No mouse Greb1 gene expression was observed in the tissues and cell clone (Yummer1.7) from the mouse BRAFV600E; PTENflox melanomas nor in B16BL6 and B16F10 mouse melanoma cell lines expressing MITF target gene (Pmel)." (PMID 37658191, 2023).
neuroblastoma (3 papers, 2020 to 2024). Neuroblastoma (NB) is the most common solid, extracranial childhood tumor. "Following 21 days of treatment with 20 μmol/L of tazemetostat, we observed an induction in GREB1 and SPTBN2, genes previously shown to be transcriptionally repressed by H3K27me3 in neuroblastoma cells." (PMID 38837897, 2024). "GREB1, adjacent to the MYCN amplicon, has crucial pro-oncogenic functions independently of MYCN in MYCN-amplified neuroblastoma." (PMID 37611092, 2023).
Uterine Tumors (3 papers, 2020 to 2025). "This case provides further evidence that uterine tumors with GREB1-rearrangement may have a high recurrence/metastasis risk." (PMID 32921307, 2020). "These limited recurrent cases specify that uterine tumor/sarcoma with GREB1-rearrangement or ESR1-NCOA2 fusions may have a high risk of recurrence/metastasis." (PMID 32921307, 2020). "First, GREB1-rearranged uterine tumours as a group displayed a greater degree of genomic complexity with more extensive copy number alterations than conventional UTROSCTs, including those harbouring ESR1::NCOA2/3." (PMID 41424301, 2025). "UTROSCTs with growth regulation by estrogen in breast cancer 1 (GREB1)-rearrangement or GREB1-rearranged uterine tumors are exceptionally rare, with only 12 previously reported cases." (PMID 32921307, 2020). "GREB1-rearranged uterine tumors often show prominently fascicular spindle cells or trabecular/cord-like arranged epithelioid cells and an inconspicuous immunophenotype of sex-cord differentiation." (PMID 32921307, 2020). "Seven cases of GREB1-rearranged uterine tumors were previously summarized; of these, six cases had follow-up information, and two cases developed pelvic dissemination and/or lung metastasis with more than 1 year of follow-up." (PMID 32921307, 2020). "Of these 13 cases of GREB1-rearranged uterine tumors, eight cases (including our case) had a definite pathological diagnosis of UTROSCT, with typical morphological and/or immunohistochemical features." (PMID 32921307, 2020). "Although the case number is limited, the higher recurrence rate of GREB1-rearranged or ESR1-NCOA2 fusion uterine tumors could indicate that these types have a greater tendency of aggressive behavior." (PMID 32921307, 2020). "Interestingly, both GREB1- and ESR1-rearrangement have been described in uterine tumors other than UTROSCTs, namely adenosarcoma and leiomyosarcoma." (PMID 40150134, 2025).
bladder cancer (2 papers, 2019 to 2021). "Alternatively, the knockdown of growth-regulating estrogen receptor binding 1 (GREB1) eRNA enhances apoptosis and represses proliferation in bladder cancer." (PMID 33568070, 2021).
endometrial cancer (2 papers, 2016 to 2018). Primary or metastatic malignant neoplasm involving the endometrium (mucous membrane that lines the endometrial cavity). "One study reported a positive correlation between GREB1 expression and ERα activation in endometrial cancer." (PMID 30154312, 2018). "Given that endometrium exposed to estrogen in the absence of progesterone is prone to hyperplasia and carcinogenesis and that GREB1 is regulated by both hormones, it seems likely that GREB1 contributes to endometrial cancer." (PMID 30154312, 2018). "Given that NCOA2, which is also called SRC-2, regulates the progesterone-dependent transcriptional regulation of GREB1 in human endometrial cells, additional studies are required to determine the role of this fusion gene in endometrial cancer onset and progression." (PMID 30154312, 2018).
Obesity (2 papers, 2014 to 2020). Accumulation of substantial excess body fat. "The GREB1 region harbours many other SNPs reported to be genome-wide significantly associated with other traits and conditions, with GREB1 in particular associated with obesity-related traits." (PMID 24676469, 2014).
pancreatic cancer (2 papers, 2016 to 2019). "GREB1 at 2p25.1 is an early response gene in the estrogen receptor (ER)-regulated pathway, and promotes growth of breast and pancreatic cancer cells." (PMID 31649266, 2019).
sarcoma (2 papers, 2020 to 2025). A usually aggressive malignant neoplasm of the soft tissue or bone. "In fact, in GREB1-rearranged tumors, it has been reported that sex cord-like features are less represented than in ESR1-rearranged tumors; the term “GREB1-rearranged sarcoma” has also been proposed to distinguish these tumors from classical UTROSCT." (PMID 40150134, 2025). "Five patients were initially diagnosed as having undifferentiated uterine sarcoma with nuclear uniformity, GREB1-rearranged sarcoma, atypical mesenchymal tumor, and sarcoma, not otherwise classifiable (cases 1, 2, 3, 4, and 6, respectively)." (PMID 32921307, 2020).
uterine sarcoma (2 papers, 2018 to 2020). "To date, 12 cases of GREB1-rearranged uterine sarcoma have been reported in the English literature; the current case is the 13th known case." (PMID 32921307, 2020). "GREB1 may also participate in uterine sarcomas, which constitute 8% of uterine corpus cancers and are derived from myometrial, mesenchymal, or undifferentiated cells." (PMID 30154312, 2018). "We found that GREB1 is transcriptionally activated by SRC-2 via the progesterone–PR axis in endometrium, and a novel fusion gene, GREB1-SRC-2, was detected in uterine sarcoma." (PMID 30154312, 2018).
arthrosis (1 paper, 2024). "Potential novel associations included COLGALT2 and arthrosis (rs35937944, p.Tyr212Cys, P = 2 × 10−14), LGR5 and carcinoid syndrome (rs200138614, p.Cys712Phe, P = 4 × 10−9), and GREB1 and female infertility (rs755857714, p.Arg1339His, P = 4 × 10−9)." (PMID 39563277, 2024).
brain tumor (1 paper, 2023). "To further validate our finding that MNA+ cancers may deploy a GREB1-dependent mechanism to drive expression of pro-oncogenic genes such as MYO1B, independently of MYCN, we investigated medulloblastoma (MB), a childhood brain tumor that also harbors recurrent MNA." (PMID 37611092, 2023).
Hearing impairment (1 paper, 2019). A decreased magnitude of the sensory perception of sound. "ATE1 (Unigene0043244), TPRN (Unigene0030527), TRIOBP (Unigene0033824), GREB1 (Unigene0021168), and DPY19L2 (Unigene0017291) are thought to be related to nonsyndromic hearing impairment by damaging structures in the inner ear." (PMID 31528181, 2019).
leiomyoma (1 paper, 2018). A well-circumscribed benign smooth muscle neoplasm characterized by the presence of spindle cells with cigar-shaped nuclei, interlacing fascicles, and a whorled pattern. "Two variants at the GREB1 locus, the missense variant rs10929757 (Asn77Thr) and rs148143917 (upstream variant), associate with leiomyoma." (PMID 30194396, 2018).
male infertility (1 paper, 2025). The inability of the male to effect fertilization of an ovum after a specified period of unprotected intercourse. "Similarly, GREB1L has recently been proposed as a marker for male infertility in mammals, and its paralog GREB1 is involved in estrogen-dependent functions of Sertoli cells." (PMID 40839421, 2025).
melanocytic nevus (1 paper, 2023). A neoplasm composed of melanocytes that usually appears as a dark spot on the skin. "In the nests of melanocytic nevus, co-staining of GREB1 and MITF and some scattered brown melanin pigments were observed." (PMID 37658191, 2023).
mucinous ovarian cancer (1 paper, 2018). An invasive malignant neoplasm that arises from the ovary and is characterized by the presence of malignant epithelial cells that contain intracytoplasmic mucin and may resemble the epithelial cells of the endocervix or gastrointestinal tract. "Serous, endometrioid, and mucinous ovarian cancers were almost always positive for either ESR1 or GREB1, suggesting a possible reliance on signalling through ESR1 and/or GREB1." (PMID 29973689, 2018).
nevus (1 paper, 2023). Nevus (or naevus, plural nevi or naevi, from nævus, Latin for "birthmark") is the medical term for sharply circumscribed[1] and chronic lesions of the skin or mucosa. "Strong GREB1 or MITF staining (score 3) was observed in 12/20 (60.0%) benign nevus samples." (PMID 37658191, 2023).
postmenopausal osteoporosis (1 paper, 2019). Metabolic disorder associated with fractures of the femoral neck, vertebrae, and distal forearm. "Because both estrogen and androgen are strong modulators of bone remodeling, it is plausible that Greb1 is a target for both further osteoporotic research and a target for the prevention and treatment of postmenopausal osteoporosis." (PMID 31844829, 2019).
prostate tumors (1 paper, 2019). "Of these, we prioritized GREB1 for further characterization because GREB1 mRNA levels are increased in primary prostate tumors that have high AR activity." (PMID 30644358, 2019). "(F) The correlation between RNA levels of GREB1, GHRHR and KLF8 and AR score in 333 TCGA primary prostate tumors were analyzed using Pearson’s correlation analysis (r)." (PMID 30644358, 2019). "Specifically, we found a statistically significant positive correlation (r) between GREB1 RNA level and AR output score across the primary prostate tumors from the TCGA dataset, but not GHRHR or KLF8." (PMID 30644358, 2019).
skin cancer (1 paper, 2023). "DepMap data from the online open-access “cancer dependency map,” which systematically identifies the genetic dependency of hundreds of cell lines, also showed that skin cancer was sensitive to GREB1 and MITF genetic perturbations." (PMID 37658191, 2023). "The GENT2 dataset also showed high GREB1 expression in skin cancer cell lines." (PMID 37658191, 2023).
testicular cancer (1 paper, 2018). A primary or metastatic malignant neoplasm that affects the testis. "In this review, we will argue that GREB1 is a good candidate for development of therapeutics for breast, ovarian, prostate, and perhaps even uterine and testicular cancers." (PMID 30154312, 2018). "No work has been done to assess the role of GREB1 in testicular cancer, but some findings suggest that GREB1 participates in testicular functions." (PMID 30154312, 2018).
uterine disorder (1 paper, 2024). A non-neoplastic or neoplastic disorder that affects the uterine corpus or the cervix. "The uterine disorders cluster (two) was significantly associated with six loci, WNT4, GREB1, BSN, SYNE1, GDAP1, and ASTN2." (PMID 39315247, 2024).
tumor (28 papers, 2011 to 2026). "GREB1-rearranged UTROSCTs showed significantly greater tumor diameter than did ESR1-rearranged UTROSCTs (7.2 ± 4.3 vs. 3.8 ± 3.3 cm; p = 0.002) and were less likely to display a submucosal exophytic growth (23.1% vs. 60%; p = 0.005)." (PMID 40150134, 2025). "Patients with high ER‐GREB1 co‐expressing tumours had favourable survival outcomes and response to ET when compared to ER+ BC lacking GREB1 expression, highlighting the role of GREB1 for a functional ER pathway." (PMID 40937605, 2025). "Tumor expression of ER target genes progesterone receptor (PR), growth-regulating estrogen receptor binding 1 (GREB1), and trefoil factor 1 (TFF1/pS2) were all significantly elevated in E2-treated HFD- versus LFD-fed females." (PMID 37608351, 2023). "Of the nine reported cases of GREB1-rearranged tumor with follow up, four cases recurred or metastasized (44.4%)." (PMID 32921307, 2020). "GREB1 was frequently detected together with β-catenin in the tumor lesions of HB patients, and GREB1 inhibited TGFβ signaling, and thereby promoting HB cell proliferation." (PMID 31462641, 2019). "YAP was indeed detected in the tumor lesions of 9 (81.8%) out of our 11 HB cases, and all nine cases were also positive for GREB1 and β-catenin." (PMID 31462641, 2019). "Tumor nodules of BYM model expressed mRNAs of GREB1 and TACSTD1 higher than those of BY or BM model." (PMID 31462641, 2019). "Both GREB1 ASOs suppressed HepG2 tumor formation and reduced tumor weight compared with control ASO." (PMID 31462641, 2019). "GREB1 ASOs-6921 and −7724 also decreased the number of Ki-67-positive cells and increased the number of apoptotic tumor cells." (PMID 31462641, 2019). "Heatmap visualization revealed that GREB1 mRNA levels vary according to tumor nodules in individual mice, and we classified the tumors into high (C1, C4, and C6) and low (C2, C3, C5, and C7) expression groups." (PMID 31462641, 2019). "β-catenin was detected in the cytoplasm and/or nucleus of the tumor lesions of nine cases (81.8%), and all nine cases were also positive for GREB1." (PMID 31462641, 2019). "In contrast, the combination of ΔNβ-catenin, YAPS127A, and c-Met (BYM model) induced larger and multiple liver nodules throughout the liver surface and the tumor nodules highly expressed both GREB1 and DLK1." (PMID 31462641, 2019). "When HepG2 cells were grown using 3D culture conditions with Matrigel, GREB1 knockdown reduced the area of tumor sphere." (PMID 31462641, 2019). "We therefore investigated GREB1 expression by QPCR and IHC in tumours of all major histological EOC subtypes." (PMID 29973689, 2018). "GREB1 overexpression increased average tumour weight at endpoint 4.5-fold but surprisingly did not alter survival, perhaps because the average volume of ascites in these mice was lower than in control mice (0.62 ± 0.88 vs. 5.30 ± 2.41 ml)." (PMID 29973689, 2018). "Microarray analysis of E2-stimulated tumours identified Greb1 as a highly upregulated gene, and we therefore investigated its role in ESR1-mediated tumour growth." (PMID 29973689, 2018). "GREB1 showed a trend for more frequent expression in low-grade tumours and in younger women, but sample sizes were too small to draw clear conclusions." (PMID 29973689, 2018). "Notably, GATA3 correlates with hormone receptor (ER/PR) positivity (both 90% in our case), implicating estrogen-response pathways (e.g., ESR1/GREB1) in tumor biology." (PMID 40969274, 2025). "A significant difference was revealed between PR+/GREB1+ tumours and other groups (P < 0.001)." (PMID 40937605, 2025). "Additionally, there is a crucial need to investigate the molecular pathology of UTROSCT, specifically the impact of gene fusions such as NCOA, ESR1, and GREB1 on tumor behavior and prognosis." (PMID 38968462, 2024). "Given that anoikis resistance is an essential feature of aggressive tumor cells and is crucial for metastasis, we also evaluated whether GREB1 controls anoikis in three-dimensional (3D) cultures." (PMID 37611092, 2023).